POMC (proopiomelanocortin)
Diseases named in the same sentence as POMC in open-access papers (continued):
Sharing a sentence is not in itself a finding about the gene and the disease.
Obesity (continued). "Moreover, these mice also showed an increased lean mass and fat mass at 15 weeks, although the degree of obesity was less than that observed in POMC-cre;;IFT88f/f mice." (PMID 33188191, 2020). "Indeed, simultaneous ablation of arcuate anorexigenic POMC and orexigenic AgRP/NPY neurons results in mild obesity, suggesting a dominance of POMC neurons in such manipulations." (PMID 31557134, 2020). "Mutations in genes that have a physiological role in the hypothalamic leptin–melanocortin energy balance system, such as mutations in leptin, leptin receptor, POMC, prohormone 1/3 convertases (PC1/3), MC4R, are related to the currently known monogenic forms of obesity." (PMID 33261141, 2020). "Furthermore, developing diet-induced obesity often resulted from the failure of leptin mediated signaling in POMC and AgRP neurons in ARC." (PMID 32272767, 2020). "Some of the genes associated with monogenetic severe obesity are: leptin (LEP), leptin receptor (LEPR), proopiomelanocortin (POMC), MC4R, preproconvertase 1 (PCSK1), single minded 1 (SIM1), brain-derived neurotrophic factor (BDNF), and tyrosine kinase receptor tropomycin-related kinase B (TrkB)." (PMID 32982666, 2020). "Conditional disruption of neuronal cilia, either throughout the central nervous system or from pro-opiomelanocortin (POMC)-expressing cells in the hypothalamus, results in hyperphagic-related obesity in mice and is accompanied by elevated levels of serum insulin, glucose, and leptin." (PMID 33139642, 2020). "However, the hypothalamic anorexigenic POMC can also be induced as an adaptive mechanism against obesity." (PMID 32585823, 2020). "It is suggested that the MC4R signalling pathway is affected secondary to the impairment of interaction with MC4R and α-MSH in heterozygous missense POMC variants without complete POMC deficiency, and subsequently severe obesity develops in humans." (PMID 30991789, 2019). "Interestingly, persistent secretion of TNF-α by microglia in the MHB of mice fed a high fat/high carbohydrate (HFHC) diet was reported to cause dysfunction in anorexigenic neurons that produce proopiomelanocortin (POMC), a characteristic feature of obesity." (PMID 31068773, 2019). "Finally, OJe modulated some obesity-related genes, such as leptin A, ghrelin, orexin, pro-opiomelanocortin (POMC), and neuropeptide Y (NPY), in both gut and brain." (PMID 31619003, 2019). "Given the pivotal role of POMC neurons in regulating metabolic homeostasis, our research objective was to identify novel mechanisms controlling POMC neuronal activity that can be leveraged for treating obesity." (PMID 31611548, 2019). "Understanding which, and how, specific POMC-derived peptides influence energy metabolism when mice are chronically fed an HF diet might hold answers to how obesity can be prevented or treated." (PMID 30997487, 2019). "However, another group reported that POMC neuron-specific Ire1a-KO mice are resistant to diet-induced obesity with increased energy expenditure." (PMID 29457782, 2018). "SIRT1 in the POMC neurons is required to protect against high calorie-induced obesity." (PMID 30532738, 2018). "MRC4 receptor resistance - proopiomelanocortin (POMC) deficiency is also a rare cause of monogenic obesity but in these patients obesity begins in the first year of life and no autonomic dysfunction is described." (PMID 29553042, 2018). "Elevated TCPTP in POMC neurons in obesity promotes HGP and systemic insulin resistance." (PMID 30230471, 2018). "Our results showing hypothalamic DNA methylation and gene expression differences in a key physiological player, POMC, suggest the chicken as a positive/promising model having great potential for interrogating the underpinnings for, for example, obesity in humans." (PMID 29928573, 2018).
Obesity (continued). "In addition, Mfn2 expression was downregulated in mouse POMC neurons as early as 4 days after high fat diet‐induced obesity." (PMID 29068134, 2018). "Since POMC processing is incomplete even in wild-type brains, stimulating POMC production or promoting its processing might reduce body weight in obesity." (PMID 30201275, 2018). "Thus, in order to dissect the role of POMC in the regulation of glucose homeostasis independently of obesity mechanisms, we performed GTTs in arcPomc−/− mice immediately after weaning, while animals still have normal body weights." (PMID 30283405, 2018). "Since body weight is sensitive to changes in the concentration of POMC-derived peptides, understanding POMC processing can provide insights into molecular mechanisms of obesity that could be therapeutically harnessed." (PMID 30201275, 2018). "Accordingly, we reasoned that sustained/elevated hypothalamic TCPTP levels in diet-induced obesity might shift POMC neural responses so that the majority of POMC neurons are unresponsive or inhibited by insulin." (PMID 30230471, 2018). "Given this androgenic enhancement of EC tone onto VMN/ARC POMC synapses, which can also be heightened under metabolic conditions such as diet-induced obesity/insulin resistance, it was of interest to see how diet would influence glutamatergic neurotransmission within this circuit." (PMID 29973869, 2018). "Prenatal deletion of LepR in POMC neurons does not affect food intake or energy expenditure but causes obesity and reduces Pomc expression." (PMID 30304668, 2018). "It was postulated that either estrogen induces changes in a number of synapses on POMC neurons, since sex differences were detected in the previous study as well; or that leptin is involved in synapse remodeling, since leptin is elevated in obesity and targets POMC neurons." (PMID 30254630, 2018). "During obesity, there is an energy surplus and POMC levels are elevated." (PMID 29528284, 2018). "POMC is upregulated during satiety signalling to prevent obesity." (PMID 30406127, 2018). "Human hypothalamic POMC neurons might also produce β-MSH, which is associated with human obesity when mutated and inhibits feeding as potently as α-MSH when injected into mice by activating MC4R." (PMID 30201275, 2018). "The overexpression of SIRT1 in POMC neurons was able to rescue FoxO1 activation induced obesity." (PMID 30532738, 2018). "Specifically, in the hypothalamic region of the brain, elevated UPR activity has been shown to potentiate diet-induced obesity and mice overexpressing UPR effector X-box binding protein 1 (XBP1) in POMC neurons are resistant to diet-induced obesity via cell- and non–cell-autonomous mechanisms." (PMID 29457782, 2018). "Another encouraging therapeutic approach is the use of a selective MC4R agonist, which has been proven successful in the treatment of POMC-deficient obesity as well as in humans with non-genetic obesity and in non-human primates." (PMID 28592656, 2017). "Interestingly, hypothalamic modulation of autophagy in response to HFD-induced obesity specifically affects POMC neurons." (PMID 28913352, 2017). "However, investigations performed on POMC knockout revealed morbid obesity resulting from hyperphagia as well as hypometabolism, indicating that POMC neurons mainly act as anorexigenic neurons." (PMID 28690493, 2017). "These INDELs and VNTRs could be found in the obesity loci or genes from the earliest GWAS and candidate gene association studies, like FTO, genes in the leptin–proopiomelanocortin pathway, and UCP2/3." (PMID 28615046, 2017). "Altered POMC expression as a consequence of developmental conditions could therefore contribute to obesity later in life." (PMID 28360832, 2017).
Obesity (continued). "Moreover, in rodents and humans, blood levels of β-endorphin, a subproduct of the POMC transcript, is regulated differently in obesity-prone and obesity-resistant subjects." (PMID 27373214, 2016). "Additionally, numerous identified mQTL-SNPs cover previously identified GWAS loci for obesity, lipid and diabetes related traits e.g. POMC, GIPR, GRB10, FADS2, SORT1 and APOA5." (PMID 27322064, 2016). "CST significantly decreased the expression levels of genes encoding obesity-promoting neuropeptides (agouti-related peptide, neuropeptide Y), and increased the mRNA levels of obesity-suppressing neuropeptides (proopiomelanocortin, cocaine-and amphetamine-regulated transcript) in the hypothalamus." (PMID 27845741, 2016). "For example, mutations in SIM1, leptin receptor (LEPR), pro-opiomelanocortin (POMC), melanocortin 4 receptor (MC4R), and more recently, POU3F2 have all been associated with severe obesity, suggesting a convergence on the leptin-melanocortin pathway in association with oxytocin." (PMID 27857842, 2016). "The contribution of peripherally expressed POMC to obesity, however, is still largely unexplored." (PMID 26940669, 2016). "Genes functioning in the leptin-melanocortin pathway such as those encoding leptin (LEP), leptin receptor (LEPR), melanocortin 4 receptor (MC4R), pro-opiomelanocortin (POMC) and brain-derived neurotrophic factor (BDNF) have been implicated in the monogenic form of obesity." (PMID 26363598, 2015). "However, smoking has been implicated in appetite suppression through the POMC neural pathway, and loci in this pathway (POMC and MC4R) increase obesity risk." (PMID 26537541, 2015). "In all, these data suggested that mitochondrial dynamics, namely Mfn1 and Mfn2, in NPY/Agrp and POMC neurons may play a role in the central regulation of energy balance and in etiology of diet induced obesity." (PMID 25904870, 2015). "It was also found that the obesity related pattern of DNA hypermethylation was present prior to the development of obesity, leading the authors to conclude that the methylation patterns in POMC appears to occur early in embryogenesis, persist across life and is related to obesity." (PMID 24664798, 2014). "Furthermore, conditional deletion of Tsc1, an upstream suppressor of mTORC1 in hypothalamic neurons (and in beta cells of the pancreas), induces hyperphagic obesity, and hypothalamic POMC neuron-specific deletion of Tsc1 results in the same phenotype." (PMID 25309497, 2014). "We next tested whether Sirt1 overexpression in POMC neurons or AgRP neurons protects mice from diet-induced obesity by feeding them an HFHS diet." (PMID 24374551, 2014). "As hyperactivation of mTORC1 in POMC neurons leads to hyperphagia and obesity in mice, the increased phosphorylation of mTORC1 seen in the hypothalamus of Ksr2−/− animals, may contribute to their increased food intake." (PMID 24209692, 2013). "POMC neurons of the Arc are known to suppress appetite, and lack of POMC-derived peptides or electrical silencing of POMC neurons causes obesity." (PMID 23508038, 2013). "Moreover, the constitutive activation of mTOR in the hypothalamus, specifically in POMC neurons, promotes food intake and obesity." (PMID 24040371, 2013). "Selective elimination of LEPRb on either POMC or AgRP neurons produced a mild obesity phenotype." (PMID 23543912, 2013). "Global knockout of the 5-HT2C receptor (5-HT2CR) induced pronounced hyperphagia, hyperactivity, and obesity in mice, but selective re-expression of 5-HT2CRs in POMC neurons resulted in the normalization of body composition, feeding behavior, and peripheral insulin sensitivity." (PMID 23440036, 2013). "Indeed, it is useful to point out that body weight regulation is also influenced in the case of haploinsufficiency of genes involved in the development of monogenetic obesity such as the leptin gene or the POMC gene." (PMID 24367518, 2013).
Obesity (continued). "Lack of POMC in humans and mouse models leads to the development of severe obesity, ACTH deficiency, and hypopigmentation." (PMID 23964269, 2013). "Deletion of LepRb specifically from POMC and AgRP neurons in mice lead to mild obesity." (PMID 22276206, 2012). "POMC variation also influences traits such as obesity and hair pigmentation." (PMID 23028917, 2012). "We propose a model where over-reactivity of the leptin-LepRb signaling system in POMC neurons may play a role in development of neuronal leptin-resistance and obesity of high-fat diet fed mice." (PMID 22276206, 2012). "Furthermore, POMC neuron-specific inhibition of this inflammatory pathway was shown to protect against the development of hypertension despite co-existing obesity or obesogenic condition." (PMID 22328600, 2012). "We describe an individual with early onset obesity, adrenal insufficiency and a novel POMC mutation but without the typical pigmentary phenotype of red hair and pale skin." (PMID 21860632, 2011). "Interestingly, humans with mutations in POMC and MC4R and mice with targeted deletions in these genes have an obesity phenotype." (PMID 21283731, 2011). "In conclusion, POMC gene mutations should be considered in patients with early onset severe obesity, adrenal insufficiency even in the absence of red hair, especially in non-Caucasians." (PMID 21860632, 2011). "In this report, we demonstrate that hypothalamic glucose sensing is mediated by HIF activation and resulting up-regulation of POMC gene and that HIF loss-of-function in POMC neurons causes glucose desensitization to promote energy imbalance and obesity development." (PMID 21814490, 2011). "The case we report had obesity, hypocortisolism but lacked red hair which is typical for subjects with POMC mutations." (PMID 21860632, 2011). "Variants in or near LEP, POMC, MC4R, and IL-6 genes confer a significant risk to human obesity." (PMID 21390334, 2011). "However, leptin and insulin resistance are common in obesity, where the effects of leptin and insulin within the AC, and especially in the POMC/CART neurons, become less pronounced and sometimes these effects may even be absent." (PMID 40136445, 2025). "In Chandigarh, India, next-generation sequencing in children with obesity identified one pathogenic variant in the MC4R gene, one likely pathogenic variant each in the LEPR, NTRK2, and LEP genes, as well as variants of uncertain significance in the POMC and LEPR genes." (PMID 40149731, 2025). "However, previous studies suggest that global hypothalamic FASN deletion does not impair neuronal survival, as it would be incompatible with life, and POMC defiency leads to obesity-related phenotypes, arguing against major developmental disruptions in POMC neurons." (PMID 40541585, 2025). "Moreover, an MC4R agonist, setmelanotide (Set), which has a 20-fold MC4R selectivity compared with α-MSH, has been effective for weight loss in patients with the MC4R/POMC/leptin pathway polymorphism and has been approved by the FDA for treatment of obesity in these patients." (PMID 40232848, 2025). "POMC neuron-specific Cpe deficiency did not cause obesity in mice." (PMID 40702736, 2025). "In addition, TLR4 deficiency in pro-opiomelanocortin (POMC) neurons can promote heat production and maintain a balance of lipid metabolism, but this ability only exists in male mice, which in turn increases the induction of obesity in female mice." (PMID 38275739, 2024). "Indeed, constitutive POMCCre mice displayed Cre expression not only in POMC neurons, but also in other neuronal populations, which may have contributed to the pronounced obesity phenotype in POMCCre mice relative to POMCCreET2 mice." (PMID 38223458, 2024).
Obesity (continued). "Notably, independent of dietary conditions, adult-onset deletion of p62 in POMC-positive neurons led to the acquisition of an obesity phenotype, which was characterized by increased energy intake and BW, and reduced energy expenditure, while mice overexpressing p62 acquired a lean phenotype." (PMID 39479445, 2024). "The early onset of severe obesity, hyperphagia, persistent diarrhea, and metabolic abnormalities may be linked to mutations in the gene SRC-1, that inhibit the leptin-induced synthesis of POMC." (PMID 37512517, 2023). "Hence, maternal nutrition in pre- and postnatal periods may alter appetite and obesity-related phenotype by influencing POMC gene methylation, and this may be transferred to childhood and adulthood." (PMID 37252665, 2023). "In addition, changes in the expression endopeptidases that convert POMC into further neuropeptides, such as PC1/3, PC2, and furin, have also been implicated in the development of obesity and might be altered following maternal hyperglycemia." (PMID 37396180, 2023). "However, it is not approved for treating obesity in individuals not impacted by POMC, PCSK1, LEPR deficiency, or Bardet-Biedl syndrome." (PMID 37937009, 2023). "In contrast to investigations concerning human obesity, association analyses conducted in canines exhibit diminished statistical power, and the outcomes are frequently lacking validation within separate populations (except POMC)." (PMID 37799139, 2023). "However, a chronic gain of function in POMC neurons through chronic activation, or overexpression of POMC or its derived peptides, fails to cause an effect on body weight reduction or obesity prevention/reversal." (PMID 37069175, 2023). "POMC deficiency and the resulting lack of POMC-derived peptides is associated with severe obesity in humans and rodents and hence impaired POMC processing might mediate hyperphagia in individuals with PC1/3 deficiency." (PMID 35963866, 2022). "Loss of STAT3 in POMC neurons leads to modest obesity in female mice but does not affect male mice." (PMID 33826123, 2022). "Actually, not only homozygous POMC mutation, but also heterozygous point mutations, which lead to disrupted alpha-melanocyte-stimulating hormone/beta-melanocyte-stimulating hormone (α-MSH/β-MSH, products of the POMC gene), could also cause obesity." (PMID 33826123, 2022). "Moreover, excess STAT3 activity inhibited POMC expression in the hypothalamus of diet-induced obesity mice, implying that STAT3 inhibition may promote leptin signaling." (PMID 34944525, 2021). "Currently described non-syndromic forms of mendelian obesity comprise mainly genetic defects in the leptin/melanocortin pathway, such as mutations in the genes encoding LEP, LEPR, prohormone convertase 1 (PC1/3), proopiomelanocortin (POMC) and melanocortin receptor 4 (MC4R), leading to overeating." (PMID 33800718, 2021). "Thus, VMN PACAP/ARC POMC synapses constitute a critical anorexigenic component of the homeostatic energy balance circuitry, one that is accentuated by E2 in females and attenuated by obesity in males." (PMID 33800452, 2021). "The deletion of STAT3 in the CNS leads to severe obesity with accompanying decreased POMC expression, whereas STAT3 inactivation in POMC neurons causes slight obesity and diminished POMC expression, which suggest STAT3 as a transcriptional activator of POMC expression." (PMID 33849593, 2021). "Biallelic loss-of-function variants in the POMC gene give rise to a phenotype with a triad of clinical features: ACTH deficiency that is usually the first to be recognized, hypopigmented skin with red hair, and early onset obesity due to uncontrolled polyphagia." (PMID 34177811, 2021). "Similarly, obesity has been reported due to mutations affecting prohormone convertase 1 gene (PCSK1), one of the enzymes responsible for proteolytic cleavage of POMC to its neuroactive derivatives, either singly or as part the more complex genetic condition Prader–Willi Syndrome." (PMID 33233816, 2020).